FOXM1 (forkhead box M1)
Diseases named in the same sentence as FOXM1 in open-access papers (continued):
Sharing a sentence is not in itself a finding about the gene and the disease.
cancer (continued). "In this study, we performed a prognostic analysis and showed that high level of either HMGA1 or FOXM1 was associated with poor prognosis in various cancers based on the TCGA database." (PMID 37240870, 2023). "FOXM1 is an oncogene that is overexpressed in many cancers and has been clinically associated with a worse prognosis." (PMID 36816948, 2023). "The focus of this study is the forkhead box protein M1 (FOXM1), which is identified as a potential therapeutic target for cancer immunotherapy and is associated with the modulation of PD‐L1 expression." (PMID 35975458, 2022). "Several studies have shown that FOXM1 overexpression was associated with aerobic glycolysis in some cancer cells." (PMID 35656815, 2022). "Noticeably, accumulating evidence indicates that HIF-1α has been implicated in driving EMT in cancer by regulating several key pathways, such as Twist, Snail and Forkhead box M1 (FoxM1)." (PMID 34969360, 2022). "Previous research demonstrated that elevated FOXM1 levels enhance cancer progression and are associated with various aggressive and chemotherapy-resistant human cancers." (PMID 35842667, 2022). "Loss of FOXM1 has been shown to lead to mitotic decline, senescence, and necrosis in both aging and in cancer treatment with FDI-6." (PMID 36010951, 2022). "FOXM1, a proliferation-associated transcription factor, is overexpressed in a variety of human tumors as a key driver of tumorigenesis and cancer progression, and is a potential anticancer therapeutic target." (PMID 36171633, 2022). "In a previous study, FOXM1 was reported to be closely associated with tumorigenesis, and upregulation of FOXM1 in most human cancers conveyed poor prognosis in patients." (PMID 35013157, 2022). "The Forkhead box protein M1 (FoxM1) is an appealing target for anti-cancer therapeutics as this cell proliferation-associated transcription factor is overexpressed in most human cancers." (PMID 35884976, 2022). "From TCGA databases, we found that FOXM1 is aberrantly overexpressed in most cancer types and that its high expression was associated with worse survival outcomes." (PMID 36357378, 2022). "Recent large-scale pan-cancer analyses have shown that overexpression of FOXM1 is common in cancer and tightly associated with dismal outcome." (PMID 35794249, 2022). "It has been demonstrated that CENPA, MYBL2, and FOXM1 were linked to numerous cancer-specific enhancers, and their elevated expression levels were associated with a poor survival rate of NSCLC patients." (PMID 35721149, 2022). "It has been found that FoxM1 is frequently dysregulated in multiple cancers, and is emerged as an important molecule implicated in the initiation and progression of cancer." (PMID 33526768, 2021). "Several studies have implicated Nrf2 and FoxM1 in tumorigenesis, as they are upregulated in various types of cancers and are dependent on oncogenic signaling downstream of Ras activation." (PMID 34798428, 2021). "Expression of FOXM1 in malignant tumors was shown to associate with high-grade disease, therapeutic resistance and poor prognosis." (PMID 33668819, 2021). "FOXM1 has been implicated in all major hallmarks of cancer and a major meta-analysis of expression signatures from ~ 18,000 human cancers identified the FOXM1 regulatory network as a major predictor of adverse outcome." (PMID 34711181, 2021). "The oncogenic transcription factor FOXM1 is overexpressed in many cancers and associated with poor patient outcomes." (PMID 34944900, 2021). "FOXM1 overexpression is known for its association with resistance to anti-cancer drugs, especially to DNA-damaging agents." (PMID 34381718, 2021). "For example, upregulation of Forkhead box M1 (FOXM1) in cancer stem cells is associated with poor prognosis in a variety of tumor types." (PMID 33959615, 2021).
cancer (continued). "FoxM1 overexpression has been linked to major hallmarks of cancer, such as cellular hyper-proliferation, genomic instability, angiogenesis, metastasis and suppressed senescence." (PMID 34900697, 2021). "As a nuclear transcription factor regulating cell cycle genes, the sustained expression of forkhead box M1 (FOXM1) has been highlighted as a hallmark of nearly all human cancers." (PMID 34447693, 2021). "FOXM1 is an oncogenic transcription factor associated with cancer aggressiveness and poor patient survival." (PMID 34944900, 2021). "Pan-cancer analyses have revealed that FOXM1 overexpression is widespread in human cancer and is linked to reduced patient survival and genomic instability." (PMID 33890574, 2021). "FOXM1 (forkhead box protein M1), as a key proliferation-associated transcription factor, which maintains cancer hallmarks by activating the expression of target genes at the transcriptional level." (PMID 34584067, 2021). "FOXM1 is abnormally overexpressed in multiple cancers, causing abnormal functioning of malignant cells." (PMID 34496842, 2021). "Previous studies have shown that increased expression of FOXM1 is highly associated with drug resistance, reduces cellular sensitivity, and protects cancer cells from induced apoptosis by chemotherapy agents." (PMID 34181359, 2021). "Augmented level of FoxM1 is implicated in drug resistance of cancer cells, including hepatic tumor cells." (PMID 34900697, 2021). "FBXW7 is a major tumor suppressor that is frequently mutated in cancer, and part of its effect can likely be attributed to the post-translational repression of FOXM1." (PMID 34298659, 2021). "The data from these GEMM models are in agreement with our pan-cancer analysis, which linked FOXM1 mRNA and protein expression to genomic instability." (PMID 34205406, 2021). "While FoxM1 and C-met are related to the active proliferative ability of cells in different types of cancer, Inppl1 is associated to a bad prognosis in HCC patients." (PMID 34737944, 2021). "FoxM1 gene encodes a protein corresponding to an important transcription factor for cell cycle progression and therefore, cancer." (PMID 34737944, 2021). "In normal cells, FOXM1 is primarily responsible for cell proliferation, while in cancer cells, FOXM1 is the hallmark of all cancers described by Hanahan and Weinberg." (PMID 34252882, 2021). "The results indicated that miR-552 was closely associated with FOXM1 expression in the 73 cancer tissues." (PMID 33867818, 2021). "Forkhead box M1 (FOXM1), a well-known oncogenic transcription factor, has been implicated in the progression of multiple cancer types." (PMID 33867818, 2021). "The aberrant up-regulation of the oncogenic transcription factor Forkhead box M1 (FoxM1) is associated with tumor development, progression and metastasis in a myriad of carcinomas, thus establishing it as an attractive target for anticancer drug development." (PMID 34900697, 2021). "On the other hand, in view of the evidences that overexpression of FoxM1 is positively associated with poor prognosis of several cancers, downregulation of FoxM1 by silencing FoxM1 mRNA currently has become one attractive strategy in cancer therapies." (PMID 32551039, 2020). "Abnormal expression of FOXM1 is detected in a variety of human cancers, including colorectal, lung, prostate, liver, and breast carcinomas, associated with cancer progression." (PMID 32365487, 2020). "FOXO3 and FOXM1 are also intimately associated with chemotherapeutic drug resistance and cancer stem cell properties." (PMID 32372224, 2020). "FOXM1 is associated with cancer metastasis, recurrence, and resistance to various chemotherapeutic drugs, such as DOX, epirubicin, and MMC." (PMID 32486251, 2020).
cancer (continued). "Nucleophosmin (NPN) was shown to sustain FOXM1 nuclear localization in cancer cells, whose mutation in AML interestingly led to FOXM1 inactivation by cytoplasmic shuttling." (PMID 33680951, 2020). "FOXM1 is reported to be associated with tumor aggressiveness and Warburg effect regulation in several cancers." (PMID 32093417, 2020). "FOXO genes are rearranged in various cancers; FOXA1 is mutated in prostate and breast tumors, while FOXM1 has been shown to be a potent outcome predictor in various cancer types." (PMID 32214027, 2020). "MELK (Maternal embryonic leucine-zipper kinase)/FoxM1(Forkhead box M1) signaling is estimated to be up-regulated in various cancers and associated with tumor growth, metastasis, angiogenesis and chemoresistance." (PMID 32581798, 2020). "There is also evidence to show that FOXM1 is regulated by B-Myb, which a key TF in the cell cycle regulation of somatic cells and implicated in different types of human cancer." (PMID 31968679, 2020). "COSMIC database has revealed several mutations and gene amplifications of FOXM1 across various cancers." (PMID 33680951, 2020). "Errantly elevated FOXM1 activity has been linked to cancer metastasis, inhibition of apoptotic pathways, and improper cell proliferation." (PMID 32805721, 2020). "In this review, we attempt to understand various mechanisms underlying FOXM1 gene and protein regulation in cancer including the different signaling pathways, post-transcriptional and post-translational modifications." (PMID 33680951, 2020). "It was reported that FOXM1 is overexpressed in a variety of cancer cells and is associated with cell proliferation and tumorigenesis." (PMID 33053721, 2020). "We also found that the high expression level of FOXM1 was significantly associated with poor prognosis in nine types of cancer." (PMID 32858881, 2020). "Bayesian network modeling showed that XKR9 is linked to important cancer‐related genes, including FOXM1, cyclin B1, and RB1CC1 (RB1 regulator)." (PMID 32920960, 2020). "The dysfunction of FOXM1 exists in almost all cancers, and has been implicated in all major hallmarks of cancer defined by Weinberg and Hanahan." (PMID 33291076, 2020). "Current research findings indicate the essential role of FOXM1 and linked the deregulation of FOXM1 to cancer progression and cancer drug resistance." (PMID 31541075, 2019). "FoxM1 is overexpressed in various human cancers, and it has been implicated in all major hallmarks of cancer, such as metastasis and chemoresistance." (PMID 31234887, 2019). "Molecular pathways implicated in cancer initiation that are inhibited by FOXO3A are similar to those increased by FOXM1." (PMID 30978209, 2019). "Various proteasome inhibitors (e.g., siomycin A and thiostrepton) targeting FOXM1 are used in cancer chemotherapy; however, they are associated with severe side effects." (PMID 31072351, 2019). "Together, these data provide significant new understanding of the nature of FOXM1 deregulation in cancer, including its causes and potential consequences." (PMID 30795624, 2019). "An inactivation of FOXO or overexpression of FOXM1 was associated with tumorigenesis and cancer progression." (PMID 31270369, 2019). "RNA expression of TOP2A, PCNA, SOX2, EZH2, ZEB1 genes associated with cell cycle, cancer cell ‘stemness’, and FOXM1‐FOXO activities was similarly affected in both cases." (PMID 30927552, 2019). "FOXO proteins typically are associated with tumor suppressive activities, whereas FOXM1 acts as an oncogene when overexpressed in several cancers." (PMID 30978209, 2019).
cancer (continued). "As a potential target of miR-4521, the databases identified FOXM1, a transcription factor which gained attention by regulating a network of genes associated with proliferation, oncogenesis and cancer progression." (PMID 31541075, 2019). "FOXM1 is associated with cancer cell proliferation and the FOXM1/Prdx3 pathway plays a role in the survival of cells, so they can be specifically targeted to develop the efficient drugs." (PMID 31500275, 2019). "In NPC cells, FOXM1 is overexpressed and it is associated with cancer metastasis and chemoresistance." (PMID 31727006, 2019). "The four remaining transcription factors retrieved as potential MRs—DACH1, EPAS1, FOXA2, and FOXM1—have been extensively reported in associations with cancers in literature." (PMID 31503425, 2019). "FOXM1 is widely overexpressed in human cancer, where its expression is associated with genomic instability." (PMID 30795624, 2019). "Prdx3 knock out mice have shown a reduction in tumor volume and metastasis giving a clue for association of Prdx3 with FOXM1 associated pathways for cancer development." (PMID 31500275, 2019). "FOXM1 expression in cancer was associated with genomic instability, as measured using aneuploidy signatures." (PMID 30795624, 2019). "Pan-cancer analyses performed here also demonstrated a significant association between both FOXM1 mRNA and protein expression and aneuploidy." (PMID 30795624, 2019). "Emerging evidence suggests that elevated FOXM1 levels promote cancer progression and are associated with a variety of aggressive and chemotherapy resistant human cancers." (PMID 30728402, 2019). "This study provides significant and novel information regarding the frequency, causes, and consequences of elevated FOXM1 expression in human cancer." (PMID 30795624, 2019). "FOX proteins are also associated with major aspects of the hallmarks of cancer, as described for FOXM1 and indicated by our literature text-mining analysis using Cancer Hallmarks Analytics Tools." (PMID 30360388, 2018). "Emerging evidence has reported that aberrant upregulation of FoxM1 and β-catenin are closely associated with aggressiveness of human cancer." (PMID 29423068, 2018). "An interesting note is that a strong positive correlation exists between ESPL1 (gene that encodes Separase protein) and FoxM1 transcripts across various human tumor tissues, suggesting a relationship between FoxM1 and Separase expression in human cancer." (PMID 29780443, 2018). "FOXM1 is overexpressed in taxane-resistant cancer cells, and the depletion or elevation of FOXM1 accordingly changed the expression levels of CSC-associated molecules." (PMID 29752436, 2018). "FOXM1 overexpression is associated with an increase in proliferation and tumorigenecity of cancer cells." (PMID 30167084, 2018). "For example, changes in the expression levels of FOXM1 or FOXOs are highly associated with chemoresistance and poor prognosis in cancer patients." (PMID 30360388, 2018). "We propose that early detection and selective targeting of FoxM1-expressing fibrotic fibroblasts will mitigate the adverse events associated with lung irradiation and improve long-term outcome in cancer survivors." (PMID 29789556, 2018). "FOXM1 is a oncogenic transcription factor which is overexpressed in various types of cancer and implicated to have critical roles in cell migration, invasion, angiogenesis and metastasis." (PMID 27999212, 2017). "FOXM1 is also associated with resistance development against numerous anti-cancer drugs (e.g. cisplatin, paclitaxel, docetaxel, gefitinib, epirubicin and trastuzumab)." (PMID 28498805, 2017). "More importantly, overwhelming evidence reveals that FoxM1 is implicated in different phases of cancer development, and all major hallmarks of cancer delineated by Hanahan and Weinberg." (PMID 28953239, 2017).
cancer (continued). "FOXM1, forkhead box protein, is a crucial cell cycle regulator, which has been shown to be highly associated with multiple cancer types." (PMID 29100329, 2017). "FOXM1 is also linked to angiogenesis, cellular senescence, DNA damage response, drug resistance, cancer stem cell renewal and differentiation of cancer." (PMID 28427178, 2017). "In ER-positive breast cancer, overexpression of FOXM1 is associated with endocrine resistance and invasiveness because it favors the expansion of stem-like cancer cells." (PMID 28666461, 2017). "We also found that an overexpression hallmark of many carcinomas, FOXM1, was significantly inhibited by CXB in OSCC cells." (PMID 28740192, 2017). "The qMIDS assay therefore represented the first FOXM1-based cancer diagnostic test which was previously validated on patients living in the UK and Norway." (PMID 27409343, 2016). "To address the importance of acetylation in regulating the growth of cancer cells, we subcutaneously injected the immune-deficient nude mice with HeLa cells stably expressing FOXM1-WT or FOXM1-5KR." (PMID 27542221, 2016). "The forkhead box M1 (FOXM1) transcription factor gene has been implicated in almost all human cancer types." (PMID 27409343, 2016). "FoxM1 is a key transcription factor in cancer implicated in the regulation of angiogenesis, migration, invasion and metastasis." (PMID 27259271, 2016). "Nucleophosmin (a protein associated with the nucleolus) directly interacts with FOXM1 and alters its localization and levels in cancer cells [R14]." (PMID 27074562, 2016). "FOXM1 overexpression has been confirmed in a wide range of human cancers and, also, associated to induction of human epithelial progenitor cell expansion." (PMID 27612430, 2016). "We are presenting the first study comparing different ethnic groups and gene expression levels in HNSCC using a FOXM1-based cancer diagnostic system." (PMID 27409343, 2016). "FoxM1 is a typical proliferation-associated transcription factor overexpressed in numerous cancer-cell lines and human cancers, implicated in cell migration, invasion, angiogenesis, and metastasis." (PMID 27517622, 2016). "Evidence of FOXM1 having a significant role in DNA damage response, cancer drug resistance and its overexpression associated with GBM tumorigenicity, make it a promising and potential radiosensitizing target for GBM therapy." (PMID 27764801, 2016). "FOXM1 is frequently overexpressed in many human cancers, and its expression is associated with poor cancer outcomes." (PMID 27351131, 2016). "FOXM1 is ubiquitously expressed in cells undergoing proliferation, and overexpression of FOXM1 is associated with poor prognosis in various malignant tumors including breast cancers." (PMID 27857161, 2016). "To uncover the mechanism of H19 regulation in GBC, we discovered that H19 shared miR-342-3p response element with FOXM1, an important oncogene that has been reported to be associated with many cancers." (PMID 27716361, 2016). "FOXM1-positive tumors were also significantly associated with cancer progression in these three subgroups (P = 0.004, 0.015, and 0.009, respectively)." (PMID 25537512, 2015). "FOXM1 has been shown to be upregulated in multiple cancer types causing increased proliferation, survival and migration." (PMID 25905460, 2015). "FOXM1 is frequently overexpressed in cancer and is linked with many processes involved in oncogenesis, such as metastasis, cancer stem cell proliferation, and angiogenesis." (PMID 26100407, 2015).